KMT2A (lysine methyltransferase 2A)
Diseases named in the same sentence as KMT2A in open-access papers (continued):
Sharing a sentence is not in itself a finding about the gene and the disease.
cancer (continued). "The strongly predicted upstream drivers for the MCF-7 GRIP dataset included mainly cancer drivers (MYC, KMT2A) and cancer associated genes (ATF4)." (PMID 27097319, 2016). "In other cancer types the relevance of KMT2A function is less clear." (PMID 39887730, 2026). "Querying the Cancer Dependency Map86, 87 for dependencies of 757 cancer cell lines on KMT2A and Menin revealed a clear trend of many cancer cell types to be dependent on KMT2A and/or Menin." (PMID 39887730, 2026). "It should be considered that ZMYND11’s important roles in neuronal development and in cancer may both be mediated through inhibition of KMT2A." (PMID 41279818, 2025). "One focus is on KMT2A/MLL1, as this catalytic subunit is well described in cancer." (PMID 41157092, 2025). "KMT2A plays a multifaceted role in cancer, promoting tumor invasion and metastasis in colorectal cancer, driving oncogenesis in aggressive lymphoid and myeloid leukemias, and influencing cell viability, migration, and apoptosis in cervical cancer through modulation of apoptosis-related proteins." (PMID 38791111, 2024). "Given these multifaceted functions, KMT2A aberrations, including both genetic alterations and epigenetic dysregulation, often drive the pathogenesis of diverse human disorders, including neurodevelopmental syndromes and a broad range of cancers." (PMID 39303915, 2024). "Taken together, KMT2A/MLL1 was identified as a positive regulator of cancer stemness." (PMID 36674511, 2023). "KMT2A was also demonstrated as essential for mediating cancer stemness in solid tumors." (PMID 36674511, 2023). "Importantly, targets of PHDs overlap with KMT2A targets and are enriched in genes involved in the cancer pathways." (PMID 36598580, 2023). "The Mixed-Lineage Leukaemia (MLL/KMT2A) gene is frequently rearranged in childhood and adult acute leukaemia (AL) and in secondary leukaemias occurring after therapy with DNA topoisomerase targeting anti-cancer agents such as etoposide (t-AL)." (PMID 36629017, 2023). "While structural rearrangements of KMT2A have long been recognized as a key feature of this rare cancer, many components regarding the etiology of IL remain unknown." (PMID 36479909, 2023). "It would be interesting to functionally study whether the exons subject to alternative splicing (such as KMT2A exon 10) are dispensable to the host cancer cells, which may have profound implications for drug designing." (PMID 37019972, 2023). "The expression levels of KMT2A and KMT2C, as well as KMT2C and KMT2H, were the most associated across all 33 cancer types among the eight KMT2 gene members, indicating that they may share certain activities." (PMID 35058979, 2022). "Notably, six genes—MLLT3, MEIS1, PBX1, PBX3, HOXA10, KMT2A—were found to play a role in transcriptional dysregulation in cancer." (PMID 35743243, 2022). "Multiple cancer-associated genes are significantly downregulated in the translatome upon shMSI1 inhibition, including MAP3K13, transcriptional enhancers of MYC and genes essential in early development, NPM1 and KMT2A, respectively." (PMID 36473869, 2022). "The overlap of these two independent analyses (N = 455) provided a cross-validated gene set, hereafter referred to as the cancer core transcriptome, that differentiates KMT2A-rearranged B lymphoblasts from their closest normal cell correlate (i.e., ELPs), which we annotated in five ways." (PMID 35288693, 2022). "First-generation inhibitors of KMT2 function, which target the wild-type and fusion proteins of KMT2A, have now been developed within the research setting and may represent a future, novel treatment strategy for multiple cancer entities." (PMID 34045664, 2022). "The same lack of predisposition to cancer development was observed in patients with haploinsufficient germline KMT2A mutations (one allele is mutated, one is not, and the concentration of the gene product is decreased)." (PMID 33302406, 2020).
cancer (continued). "In the vast majority of cancers, all the reported KMT2A mutations are heterozygous, which means that at least one wt KMT2A allele is not altered." (PMID 33302406, 2020). "The presence of wt KMT2A is also crucial in other types of cancers in which KMT2A is overexpressed." (PMID 33302406, 2020). "Finally, our present study revealed that KMT2A epigenetically promotes cancer progression by targeting CTSZ, which has specific functions in cancer invasion and metastasis." (PMID 31090199, 2019). "Moreover, KMT2A knockdown suppressed tumorsphere formation and the expression of cancer stem cell markers, which was also reversed by hTERT overexpression." (PMID 28726783, 2017). "Our results that five epidriver candidates (SRCAP, EP400, ARID1B, MBD5, and KMT2A) among the top 15 ERGs enriched in EMT fraction were found among the most mutated ERGs in clinical samples across cancer types support the driver role of EMT-specific ERG tumorigenesis." (PMID 32963031, 2020). "In addition, KMT2A depletion effectively suppressed cancer metastasis in vivo." (PMID 31090199, 2019). "Among the cell lines that are dependent on both KMT2A and MEN1 (103 lines, 13.6%) are cancer cell lines of Multiple Myeloma, Lymphoma, Prostate Cancer, Ovarian‐ and Endometrial carcinoma, Lung cancer, Kidney cancer, Breast cancer and others." (PMID 39887730, 2026). "This raises the possibility of a complementary role for SETD2 and ZMYND11 in antagonizing cancer development, forming a coordinated axis in which SETD2-catalyzed H3K36me3 promotes ZMYND11 recruitment and inhibits KMT2A." (PMID 41279818, 2025). "In contrast to KMT2A and KMT2B, KMT2C and KMT2D inhibit cell proliferation and are often considered tumor suppressors in different types of cancer." (PMID 38791111, 2024). "In conclusion, we have shown that clustered PHD domains direct KMT2A and KMT2C-D to a subset of active promoters (in particular close to TSS) and to a lesser extent to active enhancers of cancer-related pathways." (PMID 36598580, 2023). "Some of the most prevalent included known pediatric cancer fusions RUNX1::RUNX1T1 (15% AML participants), KMT2A::MLLT3/MLLT10 (12% AML), TCF3::PBX1 (4.4% ALL), and ETV6::RUNX1 (2.4% ALL)." (PMID 37323575, 2023). "MSAI was observed on chromosome arms 11q (containing a number of cancer genes including ATM and KMT2A) and 12p, suggestive of ongoing clonal evolution and potential selection of SCNAs during treatment in this patient." (PMID 37081523, 2023). "Thymoquinone also downregulates the expressions of containing plant homeodomain (PHD) and really interesting new gene (RING) finger domains 1 DNMT1,3A,3B, (UHRF1), HDAC1,4,9, G9A, KMT2A,B,C,D,E, and KDM1B genes in Jurkat cells and MDA‐MB‐468 cancer cell lines." (PMID 33747489, 2021). "The interaction of WDR5 with lncRNAs facilitates the recruitment of WDR5/KMT2A complexes and lncRNA-mediated gene transcription and determines the role of WDR5 as a tumorigenic agent in many cancers." (PMID 33302406, 2020). "To investigate the role of KMT2A in CRC, we first examined its expression levels in cancer and normal tissues." (PMID 31090199, 2019).
cancer (continued). "The involvement of KMT2A in regulating expression of HOX‐ and other genes important for development and stem cell function makes it an interesting epigenetic writer in a variety of cancer types and genomic backgrounds." (PMID 39887730, 2026). "Of note, the presence or absence of KMT2A alterations has no impact on survival of patients across all cancer subtypes." (PMID 39887730, 2026). "Overall, our data show that enhancer heterogeneity is highly prevalent in KMT2A::AFF1 ALL and may be a mechanism that drives transcriptional heterogeneity in cancer more generally." (PMID 40729681, 2025). "As reported in the Catalogue of Somatic Mutations in Cancer (COSMIC), in the order from most to least frequent, nonsense, frameshift, and missense mutations of KMT2A are identified in a variety of solid tumor malignancies." (PMID 39303915, 2024). "A few genes on chromosome 7 that may play a crucial role in the disease pathogenesis and phenotype of cancers are EZH2, KMT2A, SAMD9, SAMD9L, and CUX1." (PMID 39463522, 2024). "Nonetheless, these data suggest that at least in a subset of primary PCa, increased expression of KMT2A may contribute to tumor development, and that its expression in relationship to MYC activity modulates cancer progression." (PMID 36181613, 2022). "Several cancer-related genes, including BRCA1 and MLL (Myeloid/Lymphoid or Mixed-Lineage Leukemia; KMT2A, Lysine Methyltransferase 2A) contain many copies of the Alu element, which is the most abundant transposon in the human genome, accounting for about 10% its sequences." (PMID 33671579, 2021). "Among the top most significant EMT-specific hits, one-third belonged to the category of histone methylation writers, whereas several ERGs (including KMT2A, EP400, MBD5, and SRCAP) were found to be frequently targeted by genetic alterations in several cancer types." (PMID 32963031, 2020). "Skp2 plays a central role in cell cycle regulation, cellular senescence, apoptosis, metabolism, metastasis, and cancer stem cells by ubiquitinating a wide range of substrates, including p27, ORC1, Cdt1, KMT2A/MLL1 and others, for targeted degradation by the proteasome." (PMID 26497688, 2015). "The mammalian homologs of these protein families are KMT2A‐ and (polycomb‐repressive complex 2) PRC2‐complexes, which are critical in controlling homeobox (HOX) transcription factor gene expression during development and are frequently altered in various cancers." (PMID 40181550, 2026). "Therefore, the overexpression of KMT2A and KMT2C could maintain the chromatin active signature and facilitate the maintenance of stemness in cancer stem cells." (PMID 29728583, 2018). "However, many genes listed in the Cancer Gene Census as known driver genes were affected by nonsilent mutations, including genes that are frequently mutated in Western UTUC patients 11,12, such as KMT2A, C and D (27%) and ARID1A (14%)." (PMID 32292497, 2020).
tumor (180 papers, 2005 to 2025). "Whole-genome sequencing (WGS) of tumor DNA revealed somatic mutations in KMT2A and trisomies of chromosomes 5 and 14q." (PMID 40255822, 2025). "In AML, the interactions between GA in NPM1, KMT2A, and menin protein have been linked to leukemogenesis and represent new potential targets for anti-tumor therapies, including menin inhibitors (such as revumenib, ziftomenib, bleximenib, and DSP-5336)." (PMID 40867339, 2025). "Whole-genome sequencing of tumor DNA revealed somatic mutations in KMT2A and trisomies of chromosomes 5 and 14q." (PMID 40255822, 2025). "To assess the robustness of our result, we repeated our analysis using a control set of 1788 KMT2A somatic variants obtained from sequencing of tumor samples." (PMID 35727845, 2022). "Next-generation sequencing demonstrated mutations in FLT3, NOTCH2, and KMT2A, microsatellite stability, and a tumor mutational burden of 2 mut/Mb." (PMID 34292677, 2021). "The palindromes that are associated with oncogenes, such as RAD21, NBN and KMT2A, were found to have changed significantly in the tumor samples." (PMID 33298903, 2020). "MLL gene is made up of 14 exons, encoding the histone lysine methyltransferase whereby it is also called KMT2A, which harbors powerful transforming potential associated with neoplastic diseases assisted by specific partners, such as AF9 (MLLT3), AF4, and ENL (MLLT1)." (PMID 34540702, 2021). "High level of KMT2A was associated with tumor invasion and metastasis." (PMID 31090199, 2019). "Transcriptional silencing of KMT2A also resulted in reduced tumor cell proliferation, matching existing data in CMML." (PMID 39754404, 2025). "The high-CMLHMS group exhibited upregulation of genes such as TRPC4AP, NUSAP1, EFNA1, KMT2A, and NCOA6, which are implicated in chromatin remodeling, cell proliferation, and tumor progression." (PMID 40144021, 2025). "Revumenib which targets MLL1 (also known as KMT2A) has recently been approved for a series of pathway modified tumours." (PMID 41187221, 2025). "In the context of WT, the regulation of H3K4me3, particularly by enzymes like MLL (also known as KMT2A), plays a role in tumor development." (PMID 40722750, 2025). "Menin has a tumor-suppressor function in endocrine glands and is critical for leukemogenesis in a subgroup of mixed-lineage leukemia (MLL), driven by the rearrangement of the KMT2A gene, which encodes an epigenetic modifier." (PMID 35740427, 2022). "To summarize, our findings indicate that KMT2A, KMT2C, KMT2D, and KMT2H are more likely to inhibit tumor occurrence, whereas other KMT2s are more likely to promote tumor occurrence and are generally associated with poor prognosis." (PMID 35058979, 2022). "Mutation burdens differed significantly across subtypes (PKruskal-Wallis = 2.2 × 10−16), iAMP21 and KMT2A (MLL1) positive tumours having the highest and lowest burdens respectively." (PMID 34753926, 2021). "Integrated WGS and tNGS analysis clearly distinguished this tumor type from EBV-negative DLBCL due to frequent mutations in ARID1A (45%), KMT2A/KMT2D (32/30%), ANKRD11 (32%), or NOTCH2 (32%)." (PMID 34039950, 2021). "It has been shown that inhibitors blocking the histone-modulating functions of KMT2A, and related genes potently inhibit tumour cell proliferation in glioma cells, a partly by DNA methylation of NOTCH1 and NOTCH3 genomic locus." (PMID 34944837, 2021). "What’s more, two same gene mutations of KMT2A and TMPRSS2 were checked out in GFAP separated CTCs and tumor tissue." (PMID 33208163, 2020). "Knockdown of KMT2A dramatically suppressed cervical cancer tumor growth in size, volume and weight, while overexpression of KMT2A promoted tumor growth." (PMID 32436862, 2020).
tumor (continued). "In conclusion, our results demonstrate that in U-87 MG cells, KMT2A positively regulates NOTCH1 and NOTCH3, and this KMT2A–NOTCH1/3 cascade is essential for the inhibition of tumor cell proliferation." (PMID 28968975, 2017). "Our result reveals that KMT2A negatively acts on tumor growth, in contrast to our previous understanding of KMT2A as an oncogene in tumorigenesis." (PMID 28968975, 2017). "We demonstrated that KMT2A is essential for the inhibition of tumor cell proliferation by using both in vitro and in vivo models." (PMID 28968975, 2017). "Knockdown of KMT2A markedly suppressed melanoma tumor growth in size, volume and weight, whereas overexpression of KMT2A promoted tumor growth." (PMID 28726783, 2017). "Accordingly, KMT2A fusion proteins are postulated to function to induce genes of oncogenic signaling and hence induce tumor progression." (PMID 28968975, 2017). "The role of KMT2A knockdown in promoting tumor growth was further confirmed in vivo by transplanting U-87 MG cells into the brains of zebrafish larvae." (PMID 28968975, 2017). "An important insight into understanding the tumor suppressor functions of menin occurred when it was found that menin interacts with a SET1-like histone methyltransferase complex containing KMT2A (MLL) and KMT2D (MLL4 originally known as MLL2)." (PMID 21264250, 2011). "Increased KMT2A expression was shown in AML, and CMML patients compared to controls, and other groups demonstrated that high KMT2A levels were associated with tumor cell proliferation and migration in solid tumors." (PMID 39754404, 2025). "KMT2A mediates the interaction of β-catenin with consensus DNA sequences and the subsequent transcription of β-catenin targets, which consequently promotes tumor growth." (PMID 38706918, 2024). "Furthermore, KMT2 family genes, such as KMT2A, KMT2C, and KMT2D, were frequently mutated in TMB‐H or PD‐L1+ tumor samples." (PMID 33655698, 2021). "The remaining tumor (patient #S7) showed separate fusion partners to KMT2A 5′ and 3′ fragments." (PMID 32461620, 2020). "In the subnetwork related to tumor progression, the hubs from the blue module are the most connected, such as the genes Cmas, Kmt2a, Golt1b, Cdc34, Manf, Sco1, and Thoc3, followed by hubs from the light cyan (Extl2, Commd3, Wdr41, Keap1, Osbpl9) and pink modules." (PMID 32831131, 2020). "Moreover, it was demonstrated that KMT2A, together with hypoxia-inducible factor 1α (HIF1α), were overexpressed in tumor regions with reduced oxygen levels." (PMID 33302406, 2020). "Our results revealed the tumor-suppressive character of KMT2A, NOTCH1, and NOTCH3 in U-87 MG cells." (PMID 28968975, 2017). "Therefore, the xenotransplantation result revealed KMT2A knockdown to be sufficient for promoting tumor growth and angiogenesis in vivo." (PMID 28968975, 2017). "However, some of these and other potential alternative driver genes identified in wildtype tumours such as KMT2A, FANCC and ERC1 were also identified in many of the RAS/RAF mutant cases." (PMID 26506417, 2015). "Therefore, the role of KMT2A as a tumor promoter needs to be reassessed." (PMID 35058979, 2022). "Furthermore, KMT2A expression was positively correlated with tumor invasion and metastasis." (PMID 31090199, 2019). "However, the role of KMT2A in regulating tumor progression remains unclear, because most studies to date have focused on the function of the translocated KMT2A gene and the role of the fusion proteins resulting from translocation." (PMID 28968975, 2017). "When the formed tumor reached 100 mm3, the animals were randomly divided into five groups (five per group) and, respectively, intratumorally injected with the control shRNA, KMT2A shRNA, KMT2A shRNA+hTERT overexpression, vector and KMT2A overexpression once every three days for six times." (PMID 28726783, 2017).